PTF1A (pancreas associated transcription factor 1a)
Description:
Transcription factor implicated in the cell fate determination in various organs. Binds to the E-box consensus sequence 5'-CANNTG-3'. Plays a role in early and late pancreas development and differentiation. Important for determining whether cells allocated to the pancreatic buds continue towards pancreatic organogenesis or revert back to duodenal fates. May be involved in the maintenance of exocrine pancreas-specific gene expression including ELA1 and amylase. Required for the formation of pancreatic acinar and ductal cells. Plays an important role in cerebellar development. Directly regulated by FOXN4 and RORC during retinal development, FOXN4-PTF1A pathway plays a central role in directing the differentiation of retinal progenitors towards horizontal and amacrine fates.
Synonyms: bHLHa29; PTF1-p48; p48; PACA; PAGEN2
Tractability: PROTAC: ubiquitination databases record sites on it.
Gene: Protein-coding gene on chromosome 10 (23,192,312 to 23,194,245, forward strand). Ensembl gene ENSG00000168267.
Subcellular location: Nucleus; Cytoplasm
Subcellular location (Human Protein Atlas): Nucleoplasm
Pathways (Reactome):
Developmental Biology: Developmental Lineage of Pancreatic Acinar Cells; Regulation of gene expression in early pancreatic precursor cells
Gene Ontology:
Molecular function: sequence-specific double-stranded DNA binding; DNA binding; DNA-binding transcription factor activity, RNA polymerase II-specific; RNA polymerase II transcription regulatory region sequence-specific DNA binding; chromatin binding; DNA-binding transcription activator activity, RNA polymerase II-specific; E-box binding; protein dimerization activity; RNA polymerase II cis-regulatory region sequence-specific DNA binding; sequence-specific DNA binding
Biological process: cerebellum development; pancreas development; tissue development; amacrine cell differentiation; developmental process; exocrine pancreas development; regulation of DNA-templated transcription; regulation of neural retina development; regulation of transcription by RNA polymerase II; retina layer formation; generation of neurons; hindbrain development; positive regulation of DNA-templated transcription; positive regulation of transcription by RNA polymerase II; retinoic acid receptor signaling pathway
Cellular component: chromatin; cytoplasm; nucleus; transcription regulator complex
Genetic constraint (gnomAD): Loss-of-function variants: 17 observed, 12.38 expected, observed/expected ratio (o/e) 1.37, 90% interval 0.93 to 1.88. The synonymous counts are far from expectation, so gnomAD's model fits this gene poorly and the ratio says little. Missense variants: 467 observed, 319.8 expected, observed/expected ratio (o/e) 1.46, 90% interval 1.35 to 1.58. Synonymous variants: 254 observed, 157.19 expected, observed/expected ratio (o/e) 1.62, 90% interval 1.46 to 1.79.
Homologues: Orthologues: chimpanzee PTF1A (99% identical), macaque PTF1A (97% identical), pig PTF1A (95% identical), dog PTF1A (94% identical), rat Ptf1a (90% identical), mouse Ptf1a (90% identical), guinea pig PTF1A (60% identical), tropical clawed frog ptf1a (56% identical), zebrafish ptf1a (56% identical), Drosophila melanogaster Fer1 (29% identical). Paralogues in human: TWIST1 (19% identical), TWIST2 (17% identical), FERD3L (15% identical), HAND2 (15% identical), TCF15 (15% identical), HAND1 (15% identical), SCX (14% identical), TCF24 (14% identical), BHLHA9 (13% identical), FIGLA (13% identical), MSC (13% identical), TCF21 (12% identical), and 1 more.
Diseases named in the same sentence as PTF1A in open-access papers:
PTF1A is named in the same sentence as 73 diseases in open-access papers, as found by Europe PMC text mining. Sharing a sentence is not in itself a finding about the gene and the disease. The quoted sentences say what the papers report.
pancreatic cancer (42 papers, 2011 to 2026). "Forced expression of PTF1a also resulted in decreased tumor‐associated gene expression profiles which led to decreased cell proliferation, decreased pancreatic cancer stem cells (CSCs), and a significant increase in sensitivity toward gemcitabine treatment." (PMID 29719936, 2018). "With regard to pancreatic cancer, deletion of Ptf1a causes acinar to ductal metaplasia and dramatically enhances KRAS-driven acinar cell transformation in mice and downregulation is observed in human PDAC, leading to the postulation that PTF1A/p48 functions as a tumor suppressor gene." (PMID 34692545, 2021). "Diseases associated with PTF1A include pancreatic cancer and cerebellar agenesis." (PMID 29233967, 2017). "The nearest identified gene, located 20 kb downstream, is PTF1A, pancreas specific transcription factor 1a, a helix-loop-helix transcription factor promoting acinar differentiation in the pancreas and showing loss of function in pancreatic cancer." (PMID 21731750, 2011). "Mechanistically, it has been shown that atorvastatin inhibits Akt signaling via the P2X7 receptor in human pancreatic cancer cells, and expression of Akt and the P2rx7 gene is also down-regulated in atorvastatin-fed Ptf1a-Cre; lox-stop-lox-KrasG12D/+ mice." (PMID 37958351, 2023). "PD-L1−/− mice were crossed with KrasG12D/+; TgfβR2flox/flox; Ptf1a-cre mice to achieve early depletion of PD-L1 in pancreatic cancer." (PMID 35316682, 2022). "Our current study demonstrates that somatic WWOX loss combined with oncogenic activation (RasG12D) in the Ptf1a mouse model resulted in accelerated formation of ADM, PanINs, and pancreatic tumors." (PMID 36572673, 2022). "Blocking the paracrine activation of CXCR2 leads to attenuation of pancreatic tumor development, reduction of tumor angiogenesis, and prolongation of survival in Ptf1a-Cre; lox-stop-lox-KrasG12D/+; Tgfbr2lox/lox mice." (PMID 35159011, 2022). "For pancreatic tumor studies, two transgenic zebrafish models have been developed: Tg(ptf1a:eGFP-KRASG12V) and Tg(ptf1a:Gal4-VP16; UAS:eGFP-KRASG12V)." (PMID 36142160, 2022). "Primary pancreatic cancer cells from Ptf1a-Cre; lox-stop-lox-KrasG12D/+; Tgfbr2lox/lox mice secrete CXCR2 ligands including CXCL1, CXCL2, and CXCL5." (PMID 35159011, 2022). "Administration of 5-fluorouracil (5-FU)-incorporated EGFR receptor-targeted aptamers attenuates pancreatic cancer development in a pancreatic cancer mouse model (Ptf1a-Cre; lox-stop-lox-KrasG12D/+; Trp53lox/+)." (PMID 35159011, 2022). "Here, we report that combined conditional deletion of Wwox and activation of KRasG12D in Ptf1a-CreER-expressing mice results in accelerated formation of precursor lesions and pancreatic carcinoma." (PMID 36572673, 2022). "So far, most researchers have combined either Pdx1-Cre or Ptf1a-Cre mouse lines with KrasLSL-G12D mouse to develop pancreatic tumors." (PMID 33393460, 2021). "Here, we established and characterized an immortalized miniature pig pancreatic cell line derived from primary pancreatic cells and pancreatic cancer-like cells expressing K-rasG12D regulated by the human PTF1A promoter." (PMID 33233448, 2020). "Pancreatic cancer (PC) is acquired postnatally; to mimic this scenario, we developed an inducible KrasG12D; Ptf1a-CreERTM (iKC) mouse model, in which Kras is activated postnatally at week 16 upon tamoxifen (TAM) administration." (PMID 32709695, 2020). "We approached this long-standing issue by examining the following PanIN/IPMN cell lines derived from mouse models of pancreatic cancer: Ptf1a-Cre; KrasG12D; p53f/+ and Ptf1a-Cre; KrasG12D; and Brg1f/f pancreatic ductal adenocarcinomas (PDAs)." (PMID 32266133, 2020). "Next, we assessed miR181ab1 function in pancreatic tumor development using the Ptf1a+/CreKras+/LSL-G12DTrp53fl/fl (KPC181fl/fl) mutant model in which PDAC develops with 100% penetrance 6–8 weeks after birth." (PMID 31874105, 2020).
pancreatic cancer (continued). "PTF1A therefore protects against pancreatic cancer by acting as a tumor suppressor and keeping acinar cells in their healthy, differentiated state." (PMID 26151762, 2015). "Our results suggest that PTF1A restoration provides an indirect approach to target KRAS-dependency in pancreatic cancer, inhibiting this currently ‘undruggable’, although ubiquitous, cancer-driving mutation." (PMID 26151762, 2015). "Recent studies have classified ∼1/3 of pancreatic cancers as ‘exocrine-like’, and several genes that are under Ptf1a control contribute to this signature." (PMID 26151762, 2015). "The involvement of the Smad3/TGFβ signaling pathway during pancreatic tumor progression was confirmed by real-time PCR, showing a significant increase (P<0.005) in mCherry mRNA levels in Tg(ptf1a:Gal4)/UAS:eGFP-KRASG12D compared with the control." (PMID 24878567, 2014). "Indeed, preclinical studies have shown that pancreatic cancer cells can be induce to differentiate by a key pancreatic differentiation factor Ptf1a, and breast cancer cells can be induced to post-mitotic adipocytes, and leading to suppression of the cancers." (PMID 37228646, 2023). "Interestingly, in murine pancreatic cancer autochthonous model (Ptf1a-Cre; lox-stop-lox-KrasG12D/+; Trp53lox/+), CRISPR-Cas9 screening for targeting ca. 3000 metabolic genes identified Fdft1 as one of the most differentially dependent genes in vivo." (PMID 37958351, 2023). "Moreover, a significant correlation was observed in KPC (KrasLSL-G12D; Trp53LSL-R172H; Pdx1-Cre) and KTC (KrasLSL-G12D/+; Tgfbr2flox/wt; Ptf1a-Cre) autochthonous pancreatic tumors in a genetically engineered mouse model (GEMM)." (PMID 34315872, 2021). "To study the role of Mir34a in pancreatic cancer development we crossed the Mir34afl/fl mice with the well described Kras mouse model for PDAC38 to generate Ptf1a+/Cre; Kras+/LSL-G12D; Mir34afl/fl mice (hereafter called: KrasG12D; Mir34aΔ/Δ), which were analysed at specific time points." (PMID 32541781, 2020). "This study represents one of the largest systematic and comprehensive histological and metabolic profiling investigations of the most well characterized mouse model of pancreatic cancer, namely the Ptf1a-Cre; LSL-KrasG12D transgenic mouse model, reported to date." (PMID 30016349, 2018). "Given that CSCs are resistant to therapeutics, we also examined whether PTF1a expression sensitized cells to gemcitabine treatment, a standard therapy for patients with pancreatic cancer." (PMID 29719936, 2018). "Thus, MIST1 and PTF1a protect acinar cells against the development of the earliest stages of pancreatic cancer." (PMID 29719936, 2018). "Thus, we identified a strong repression of selected differentiation genes, such as Ptf1a, Rbpjl, Mist1 (Bhlha15, basic helix-loop-helix family, member a15) and Amy (alpha-Amylase) in 3D-ADMs and pancreatic tumor cells." (PMID 26716510, 2016). "Moreover, pancreatic cancer cells contain much lower levels of PTF1A than normal pancreatic cells." (PMID 26151762, 2015). "Furthermore, understanding how PTF1A function is subverted during pancreatic cancer initiation, and whether its reactivation could suppress or reverse tumor development, may yield novel approaches to prevention and treatment." (PMID 26151762, 2015).
pancreatic cancer (continued). "Pancreatic cancer patients exhibit higher GPC1+ circulating exosomes than in healthy donors, and elevated level of GPC1+ circulating exosomes is also observed in Ptf1a-Cre; lox-stop-lox-KrasG12D/+; Tgfbr2lox/lox mice." (PMID 35159011, 2022). "Treatment with exosomes carrying short interfering RNA or short hairpin RNA specific to KrasG12D suppresses pancreatic cancer progression and improves survival of KPC and Ptf1a-Cre; lox-stop-lox-KrasG12D/+; Tgfbr2lox/lox mice." (PMID 35159011, 2022). "To understand the functional role of Arid1a in development of pancreatic cancer, we generated LSL-KrasG12D; Arid1afl/fl; Ptf1a-Cre (“KAC”) mice by crossing Arid1afl/fl; Ptf1a-Cre (“AC”) mice with Lox-stop-lox KrasG12D mice." (PMID 32967217, 2020). "As a result, ductal (CA2, CK19, and SOX9)/pancreatic cancer (EpCAM and CD44) markers decreased and acinar markers (SYP and PTF1A) increased by inhibitor treatment in KiPCs." (PMID 33233448, 2020). "The transgenic Ptf1a-Cre; LSL-KrasG12D mouse strain was used as a model of pancreatic cancer progression." (PMID 30016349, 2018). "The Ptf1a-Cre; LSL-KrasG12D mouse model of pancreatic cancer is considered to recapitulate important characteristics of human pancreatic cancer, including spontaneous pancreatic tumor formation that is preceded by a precancerous PanIN stage." (PMID 30016349, 2018). "It should also be noted that we did not detect the expression of the PDX1 and PTF1A proteins in cell lysates of all the six pancreatic cancer lines analyzed (data not shown)." (PMID 35884771, 2022). "Here, the Ptf1a-Cre; LSL-KrasG12D mouse model was used to enable NMR-based metabolic profiling of urine, fecal, serum, and pancreatic tissue samples from healthy mice and mice in different PanIN stages, plus 47 mice with pancreatic tumors." (PMID 30016349, 2018). "Together, these data reveal that PTF1a and MIST1 retain functional capacity in pancreatic cancer cells and can activate their respective transcriptional networks, providing evidence that genes involved in acinar development can be reactivated in human and mouse PDAC cells." (PMID 29719936, 2018).
pancreatic agenesis (18 papers, 2013 to 2025). Partial agenesis of the pancreas is characterized by the congenital absence of a critical mass of pancreatic tissue. "Mutations in a recently identified distal developmental enhancer of PTF1A have been linked to pancreatic agenesis in 14 individuals, including 10 probands and 4 family members." (PMID 40443916, 2025). "Based on previous studies, the g.23508437A > G variant in the PTF1A gene enhancer region should be considered in cases of pancreatic agenesis." (PMID 40443916, 2025). "One of the rarest causes of NDM is pancreatic agenesis, which results from mutations affecting the pancreas transcription factor 1A (PTF1A) gene and its enhancer." (PMID 40443916, 2025). "The c.1570 + 4090 T > C mutation in the PTF1A enhancer region is believed to impair regulatory elements essential for pancreatic development, potentially causing pancreatic agenesis." (PMID 40443916, 2025). "Here, we report a 2-year-old patient diagnosed with PNDM due to pancreatic agenesis caused by a novel mutation in the PTF1A enhancer." (PMID 40443916, 2025). "A nonsense mutation involving transcription factor 1A (PTF1A) was the second gene associated with pancreatic agenesis as well as cerebellar agenesis." (PMID 39421339, 2024). "The study reported six patients with a mean age of eight years who presented with pancreatic agenesis resulting in neonatal diabetes with PTF1A gene mutation." (PMID 37854477, 2023). "Recessive mutations in a developmental enhancer of PTF1A were found in patients with isolated pancreatic agenesis." (PMID 35997367, 2022). "Recessive loss-of-function mutations in a putative enhancer located ∼25 kb from PTF1A cause isolated pancreatic agenesis, which results in neonatal diabetes and exocrine insufficiency." (PMID 35998583, 2022). "Using linkage, whole genome sequencing, and epigenomic annotation in human embryonic stem cell (hESC)‐derived pancreatic progenitor cells, autosomal recessive defects in the noncoding region of PTF1A underlying isolated pancreatic agenesis have been revealed." (PMID 31441606, 2019). "Two of these cases had isolated pancreatic agenesis due to mutations in a distal enhancer of the PTF1A gene." (PMID 28943513, 2018). "Here, we report a patient with isolated pancreatic agenesis due to compound heterozygous mutations in PTF1A: A coding frameshift mutation (p.Ala146Glyfs*116) and a novel regulatory mutation located in the distal enhancer, 25 kb downstream of this gene." (PMID 28663161, 2017). "No additional clinical features were present in these patients, consistent with the reported clinical phenotype of isolated pancreatic agenesis with distal enhancer PTF1A mutations." (PMID 25755231, 2015). "The most recent work reported that a recessive mutation in a distal enhancer region of the PTF1A gene leads to pancreatic agenesis, indicating that the non-coding region is a potential determinant of disease." (PMID 25404134, 2014). "In humans, recessive mutations of PTF1A cause cerebellar agenesis and permanent neonatal diabetes due to pancreatic agenesis." (PMID 23437000, 2013). "Biallelic mutations in the PTF1A enhancer are the commonest cause of isolated pancreatic agenesis." (PMID 32893856, 2020). "In summary, we report the case of a patient with isolated pancreatic agenesis due to compound heterozygosity for a truncating and novel enhancer mutation in PTF1A, broadening the spectrum of mutations causing pancreatic agenesis and phenotypic variability of this condition." (PMID 28663161, 2017). "Homozygous truncating mutations in PTF1A have been reported in patients with pancreatic and cerebellar agenesis, whilst mutations located in a distal pancreatic-specific enhancer cause isolated pancreatic agenesis." (PMID 28663161, 2017).
pancreatic agenesis (continued). "Homozygous truncating mutations in the PTF1A gene, which encodes a transcriptional factor, have been reported in patients with pancreatic and cerebellar agenesis, whilst mutations located in a distal pancreatic-specific enhancer cause isolated pancreatic agenesis." (PMID 28663161, 2017). "Several genes, including PDX1, PTF1A, HNF1B, and GATA6, have been implicated in pancreatic agenesis." (PMID 40443916, 2025). "Homozygous truncating mutations in PTF1A cause a severe syndrome of PNDM, central hypoventilation, pancreatic agenesis, exocrine pancreas dysfunction, and complete cerebellar agenesis associated with a very short survival period." (PMID 32893856, 2020). "Similarly, the second case only reported pancreatic agenesis without cerebellar with a reported gene mutation of PTF1A." (PMID 37854477, 2023). "Alternatively, coding mutations may cause a pleiotropic phenotype whereas enhancer mutations will only affect the tissues in which that enhancer is active, as observed in PTF1A-related cerebellar and pancreatic agenesis versus PTF1A-related isolated pancreatic agenesis." (PMID 28754144, 2017). "The three patients (case No. 1–3) with PTF1A enhancer deletion and isolated pancreatic agenesis descend from two unrelated consanguineous families." (PMID 31441606, 2019). "As such, variants in noncoding regions that can be relevant for genetic disease, such as variants in the enhancers of BCL11A and PTF1A that cause Dias-Logan syndrome (OMIM 617101) and pancreatic agenesis (OMIM 609069), respectively, were not covered in our analysis." (PMID 34078906, 2021).